PINK1 (PTEN induced kinase 1)
Diseases named in the same sentence as PINK1 in open-access papers (continued):
Sharing a sentence is not in itself a finding about the gene and the disease.
Parkinson disease (continued). "Parkinson's disease‐related proteins, PINK1 and Parkin, act in a common pathway to maintain mitochondrial quality control." (PMID 36250243, 2022). "Patients with PRKN or PINK1 also manifested the juvenile- (under 20 years of age at onset) or young-onset parkinsonism (under 40 years) with excellent response to even the low doses of levodopa, which leads to the brain pathology in the absence of LBs." (PMID 35720097, 2022). "Miro1 has emerged as an interesting target to study Parkinson’s disease-relevant pathways since it is a target of PINK1 and Parkin." (PMID 35455950, 2022). "Dysfunction of PINK1 related pathway has been reported in patients with Parkinson’s and Alzheimer’s diseases, which makes it a candidate therapeutic target for those diseases." (PMID 35847024, 2022). "Amplified mitophagy relies on both phosphorylation and ubiquitination by PINK1 and QC E3-ligase Parkin in Parkinson’s disease." (PMID 35233680, 2022). "In terms of evaluating mitochondrial dysfunction in PD, a biochemical study showed the interaction of mortalin, which is a mitochondrial heat shock protein 70 (HSP70) with key genes involved in Parkinson’s disease such as Parkin, PINK1, and DJ-1." (PMID 35859895, 2022). "Among them, the PTEN induced putative kinase 1 (PINK1)-parkin pathway is the most well-understood regarding its contributory role to neurodegenerative diseases, and particularly, to Parkinson’s disease (PD)." (PMID 33685483, 2021). "Knock-down of atg5 caused an upregulation of β-syn, (β synuclein), PINK1 (PTEN induced kinase 1) and parkin proteins, which have been related to Parkinson’s disease." (PMID 33917666, 2021). "Some of the strongest disease associated genes in Parkinson's disease encode for kinases; LRRK2 and PINK1." (PMID 33642997, 2021). "One of the peculiarities of PINK1 related parkinsonism is the incidence of dystonia, which often presents in the early stages of the disease and more frequently involves the lower limbs." (PMID 34831247, 2021). "In Parkinson's, the PTEN-induced putative kinase protein 1 (PINK1)/PARK2 gene-encoded E3 ubiquitin ligase (Parkin) signaling cascade activates mitophagy." (PMID 34987374, 2021). "In the brain tissue of Parkinson's disease patients, there are excessive dysfunctional mitochondria, and the mutation of PTEN-induced putative kinase 1 (PINK1) was identified in this tissue." (PMID 34225732, 2021). "More recently, PINK1 was found to be ubiquitously expressed in primary rat microglia; and in experimental mouse models of Parkinson’s disease, reduced PINK1 diminishes AKT activity in microglia." (PMID 34838047, 2021). "We further highlight that the discovery of natural PINK1 regulators represents an attractive strategy for the treatment of PINK1-related diseases, including liver and heart diseases, cancer, and Parkinson's disease." (PMID 34751247, 2021). "Pathogenic variants in α-syn (SNCA) gene have been also identified and associated to PD, while mutations in four genes (Parkin, DJ-1, PINK1 and ATP13A2) cause early-onset parkinsonism." (PMID 33210214, 2021). "Pink1−/− rats do show parallels to human Parkinson disease in terms of age of onset and progression of early cranial sensorimotor deficits." (PMID 33928251, 2021). "The Parkinson’s disease-linked proteins PARK2–Parkin and PTEN-induced kinase 1 (PINK1) directly interact with various components of the autophagy machinery, and constitute a common pathway triggering mitochondrial turnover." (PMID 33820826, 2021). "PINK1 was first discovered nearly 20 years ago due its dysregulation in ovarian cancer and soon after was reported to be important in the development of Parkinson's disease." (PMID 34751247, 2021). "The disruption of phosphorylation is linked with Parkinson's disease, with the mutation of PARK6 encoding an protein kinase PINK1 being the second most common cause of autosomal recessive familial Parkinson's disease." (PMID 34335440, 2021).
Parkinson disease (continued). "In hypoxic Parkinson's brain tissue, PINK1 can bind and stabilize the mitochondrial membrane after mitochondrial depolarization." (PMID 34987374, 2021). "Among AR parkinsonisms, forms caused by biallelic pathogenic variants in the PRKN, PINK1, and DJ-1 genes are thus far considered pure forms of EOPD." (PMID 34630269, 2021). "Inhibition of LRRK2 kinase activity restored defective PINK1 dependent mitophagy in Parkinson’s disease, indicating a link between PINK1 and LRRK2." (PMID 33546409, 2021). "This will allow in vitro in this cellular model of Parkinson’s disease to increase the enzymatic activity of PINK1 and to increase mitophagy." (PMID 34768767, 2021). "Two Parkinson’s disease-associated proteins, PTEN-induced kinase 1 (PINK1) and Parkin RBR E3 ubiquitin protein ligase (PRKN), are central to mitophagy and mitochondrial quality control." (PMID 33268902, 2021). "We previously demonstrated that IPAS was involved in neurodegeneration in a 1-methyl-4-phenyl-1,2,3,6-tetrahydropyridine (MPTP)-induced mouse model of Parkinson’s disease (PD), and degraded by activation of the PINK1-Parkin pathway." (PMID 33947838, 2021). "PINK1, a mitochondrial kinase, plays a role in mitochondrial quality control and is related to recessive familial Parkinson’s disease." (PMID 34354990, 2021). "PTEN-induced putative kinase 1 (PINK1) is a mitochondrial protein identified as a responsible gene in Parkinson’s disease." (PMID 34624312, 2021). "Most cases of Parkinson’s disease are sporadic ones, but there is a small percentage of cases that are due to mutations of PTEN-induced kinase 1 (PINK1), a mitochondrial kinase." (PMID 34206736, 2021). "While there are multiple mechanisms mediating mitochondrial mitophagy, undoubtedly the best studied pathway is the PINK1-PARKIN pathway, which has been well characterized as rare pathogenic variants in PINK1 and PARKIN cause Parkinson Disease." (PMID 33810506, 2021). "Biallelic variants in DJ-1 (oncogene Dj1, MIM*602533) cause a rare Parkinsonism (PARK7, MIM#606324), the third most common AR PD after the PRKN- and PINK1-related forms, accounting for the 0.4 and 1% of EOPD cases, respectively." (PMID 34630269, 2021). "The best characterized is mediated by the kinase PINK1 (PTEN-induced kinase 1) and the E3 ubiquitin ligase Parkin, mutations in both of which have been associated with autosomal recessive forms of Parkinson’s disease." (PMID 33066461, 2020). "Parkinson’s disease (PD)‐associated gene products, like Parkin and PTEN‐induced putative kinase 1 (PINK1), have been suggested to be the key components in mitochondrial quality control system." (PMID 32779864, 2020). "In MPTP-induced Parkinson's disease models, Sal can enhance the mitochondrial expression of PINK1 and Parkin and confer neuroprotective effects." (PMID 32774670, 2020). "Currently, one of the best understood and most well-studied pathways of mitophagy is the PTEN-induced putative kinase 1 (PINK1) and Parkin(PARK2) pathway, which is associated with the development of Parkinson’s disease." (PMID 32766245, 2020). "Loss of function mutations of PARK6 and PARK2 genes, which encode PINK1 and Parkin respectively, are linked to familial form of parkinsonism." (PMID 33537304, 2020). "Homozygous mutations in the PINK1 gene, encoding for PTEN-induced kinase 1, were first identified in three consanguineous families with early-onset Parkinsonism through linkage analysis in 2004." (PMID 32858900, 2020). "By participating in the recruitment of PINK1 and the E3 ubiquitin ligase Parkin, TOM70 can be implicated in the development of Parkinson’s disease." (PMID 33019591, 2020). "Mutations in the PTEN-induced kinase 1 (PINK1) and Parkin RBR E3 ubiquitin-protein ligase (PARKIN) genes are associated with familial forms of Parkinson’s disease (PD)." (PMID 33168089, 2020). "Mutations in their genes, PINK1 and PARK2 respectively, are associated with forms of early-onset Parkinson’s disease." (PMID 33019591, 2020).
Parkinson disease (continued). "Another well-studied example is the Parkinson disease protein PINK1, which promotes mitochondrial autophagy when mitochondrial import is blocked, and which can be activated by the accumulation of unfolded proteins in the matrix." (PMID 33171986, 2020). "The predisposition genes potentially linked to the neurological form of CD were identified by messenger-RNA (mRNA) profiling: CADPS2 (ASD), CAPN13 (AD), BACE2 (AD, DS), DSCR5 (DS), and PINK1 (Parkinson’s Disease (PD)." (PMID 32751379, 2020). "Parkinson’s disease susceptible genes, which encode for proteins such as leucine-rich repeat kinase 2 (LRRK2), Parkin, PINK1, and DJ-1, are localized on the mitochondria and interfere with the function of mitochondria." (PMID 32655368, 2020). "PINK1 has also shown protective effects in various neuronal disease models, including an α-synuclein-induced Parkinson’s disease model, a Huntington’s disease model, and an Alzheimer’s disease model." (PMID 32941465, 2020). "Mutations in both genes encoding PINK1 and Parkin (PARK2), have been reported to cause autosomal recessive forms of Parkinson’s Disease (PD)." (PMID 32373609, 2020). "PINK1/Parkin-mediated mitophagy has a crucial role in various diseases, such as CI/R injury, Parkinson’s disease and septic acute kidney injury." (PMID 32912324, 2020). "The two major recessive Parkinson's disease genes PINK1 and Parkin play essential roles in mitophagy initiation, increasing the interest in mitophagy in both basic and translational research over the past 10 years." (PMID 31876372, 2020). "Genetic evidence suggests that the pathways of mitochondrial quality control (PARKIN, PINK1, DJ-1, FBOX7) and mitochondrial fusion/fission dynamics (OPA1) are implicated in PD and parkinsonism." (PMID 33381501, 2020). "This signaling pathway has been studied extensively in the context of neurodegeneration because mutations in human PINK1 (PARK6) and Parkin (PARK2) are assumed to be causative for early onset Parkinson’s disease." (PMID 33343399, 2020). "Mutations in PARK2 (Parkin) and PINK1 (PTEN-induced putative kinase), that result in monogenic Parkinson disease, are believed to impact mitochondrial function by increasing susceptibility to toxins." (PMID 31464647, 2019). "Current estimates state that only 15% of PD patients carry a mutation in a known Parkinson's-related factor (e.g., LRRK2, PARK2/Parkin, PINK1, or SNCA)." (PMID 31192157, 2019). "The hereditary form of Parkinson’s disease is primarily associated with mutations in the genes encoding PARKIN and PINK1 proteins (PTEN induced kinase 1), which mediate mitophagy." (PMID 31139208, 2019). "In 2013, the Foundation developed an initiative to translate PINK1-Parkin understanding into meaningful therapies for people with Parkinson’s disease." (PMID 31344817, 2019). "Patients with severe PINK1 and PRKN mutations present early onset forms of Parkinson’s disease and have been reported in this PD cohort." (PMID 31096927, 2019). "PTEN-induced putative kinase-1 (PINK1), involved in Parkinson’s disease, activates the HIF1α mRNA translation during hypoxia by acting on 4E-BP1." (PMID 30791615, 2019). "Missense mutations in the human protein kinase PINK1 gene (PTEN-induced kinase 1, hPINK1) are thought to cause hereditary Parkinson’s disease with an early onset." (PMID 30984018, 2019). "Changes in the expression of PINK1 appear related to neurodegenerative disorders such as Alzheimer’s and Parkinson’s diseases." (PMID 31487916, 2019). "The autosomal recessive forms of Parkinson’s disease are caused by mutations of Parkin RBR E3 ubiquitin protein ligase (PARK2) and PTEN-induced putative kinase 1 (PINK1), which regulates degradation of damaged mitochondria (mitophagy)." (PMID 30744021, 2019).
Parkinson disease (continued). "These efforts seek to build on a robust and growing PD therapeutic pipeline and to translate biological understanding of the PINK1-Parkin-mitochondrial pathway to identify new targets to one day enable the development of a cure for Parkinson’s disease." (PMID 31344817, 2019). "PINK1 plays the pivotal role because its accumulation is the trigger of many neurodegenerative diseases, like Parkinson’s." (PMID 31487916, 2019). "The observation that PINK1 levels were lower in immunosuppressive DC is in contrast with the observed effects in Parkinson patients and Pink1−/− mice." (PMID 31681280, 2019). "Mitochondrial import efficiency was abnormally low in cells from patients with PINK1- and PARK2-linked Parkinson’s disease and was restored by phosphomimetic ubiquitin in cells with residual Parkin activity." (PMID 31413265, 2019). "Mutations in phosphatase and tensin homolog-induced putative kinase 1 (PINK1) and parkin are found in early-onset Parkinson’s disease and are important in the progression of Parkinsonism." (PMID 31208099, 2019). "Linkage of the PRKN and PINK1 genes to Parkinson’s disease led to some seminal papers in the field of mitochondrial biology in PD." (PMID 31344817, 2019). "The most well-known pathway is PINK1/Parkin-mediated mitophagy, named for its role in the pathogenesis of Parkinson’s disease." (PMID 28401475, 2018). "We generated homozygous Pink1/Parkin double knockout pigs as Parkinson’s disease models through a single transfection of CRISPR/Cas9 and SCNT." (PMID 30233645, 2018). "The enrichment analysis of KEGG pathways showed that the PINK1/PARKIN/DJ-1 network show Parkinson disease as the main feature." (PMID 30274236, 2018). "PGAM5 phosphatase activity is required for PINK1 stabilization as well as PINK1/Parkin-mediated mitophagy, and PGAM5-deficient mice develop Parkinson’s disease." (PMID 28401475, 2018). "Since Optn mediates its mitophagy function downstream of PINK1 and Parkin, which have been formally reported to be involved in Parkinsonism, we detailed here the genes responsible of mitochondrial dysfunctions in Parkinson disease and Parkinsonism." (PMID 29971063, 2018). "Among the genes mutated in Parkinsonism, three autosomal inherited genes have been identified by Genome-Wide Association Studies to impact mitochondrial function: PARK2 (Parkin), PARK6 (PINK1), and PARK7 (DJ-1)." (PMID 29971063, 2018). "A unique characteristic of DJ-1 that distinguishes it from other Parkinson’s disease-relevant proteins, such as PINK1 and Parkin, is its evolutionary conservation with the prokaryotic kingdom." (PMID 28993701, 2017). "Variants in PINK1 and PARK2 (parkin) cause early onset Parkinson’s disease in humans with a similar clinical presentation as DJ-1 mutations." (PMID 28962651, 2017). "A unique characteristic that clearly distinguishes DJ-1 from other Parkinson’s disease-relevant proteins such as PINK1, Parkin, and LRRK2 is its broad evolutionary conservation, which extends to the prokaryotic kingdom." (PMID 28993701, 2017). "Subsequently, also named PARK15, Fbxo7 was found to interact directly with two other genes mutated in Parkinson’s disease, PINK1/PARK6, and Parkin/PARK2, to promote mitophagy." (PMID 27915416, 2017). "As reported for PINK1 and DJ-1, these PD patients show a largely preserved sense of smell, adding evidence to the observations that autosomal dominant forms of monogenic parkinsonism exhibit more severe olfactory impairment than the recessive ones." (PMID 28458632, 2017). "Although genes have been identified that can cause Parkinson’s disease, such as SNCA, LRRK2, parkin, PINK1, and DJ-1." (PMID 28989991, 2017).
Parkinson disease (continued). "Among the candidate targets that were validated, we identified PINK1, which is studied in patients with Parkinson and cancer (especially melanoma)." (PMID 29229974, 2017). "Some of the genes that were steadily down-regulated, such as Pink1, Park 2, Sv2b, Gabbr2, Sept5 and Atxn2, were directly related to Parkinson’s onset." (PMID 29156651, 2017). "From the clinical information available for the index case, the phenotype of mild, slowly-progressive Parkinsonism is consistent with previous reports of p.A217D disease and of PINK1 disease phenotype more generally." (PMID 28789629, 2017). "Mutations in PINK1 and PARKIN cause early-onset Parkinson's disease (PD), thought to be due to mitochondrial toxicity." (PMID 27336715, 2016). "For examples, NRF1 target genes- PARK2, PARK6 (PINK1), PARK7, PAELR (GPR37) are associated with Parkinson’s disease." (PMID 27983596, 2016). "Studies in Drosophila models of Parkinson’s disease demonstrated that Parkin and PINK1 function in a common pathway that regulates mitochondrial quality control." (PMID 28536620, 2016). "We also demonstrate that the mechanism linking WFS1 deficiency-related ER stress with impaired mitochondrial dynamics involves two Parkinson’s disease-related proteins, PINK1 and Parkin." (PMID 27434582, 2016). "In a nutshell, ubiquitin was identified as the main substrate for the protein kinase PINK1, which has been intensely studied due to its genetic links to autosomal recessive juvenile Parkinsonism (AR-JP), an early onset form of Parkinson's disease (PD)." (PMID 27012465, 2016). "Mutations in six genes are known to cause Parkinson's disease (PD) (autosomal dominant: alpha-synuclein, LRRK2, VPS35 and autosomal recessive: Parkin, PINK1 and DJ1) and number of other genes are implicated." (PMID 27872751, 2016). "In one important pathway, dysfunctional mitochondria are eliminated through a process dependent on PTEN-induced putative kinase 1 (PINK1) and Parkin, loss of which lead to familial forms of Parkinson's disease." (PMID 27841259, 2016). "In conjunction with other previously published data, these data suggest identify PINK1 pathways that are constitutively altered in Parkinson׳s disease." (PMID 26866053, 2016). "Deletions and point mutations of Parkin and PINK1 genes (PARK2 and PARK6, respectively) were identified in early-onset Parkinson’s disease patients and these disease-associated mutations were shown to mechanistically result in defective mitophagy." (PMID 26611876, 2016). "Results and further interpretation and discussion can be found in the original research article “Atp13a2 expression in the periaqueductal gray is decreased in the Pink1 −/− rat model of Parkinson disease”." (PMID 27331115, 2016). "At the same time, genes related to mitochondrial QC, for example PINK1 (involved in the targeting of depolarized mitochondria for mitophagy), are also downregulated in age-related diseases, such as in neurons of Parkinson’s disease patients." (PMID 25996936, 2015). "The prototypical Parkinson's disease factor that, via its E3 ubiquitin ligase activity, plays a central role in PINK1/Parkin-mediated mitophagy." (PMID 25861797, 2015). "E3 Ub ligase Parkin (Park2) interacts with PTEN-induced putative kinase 1 (PINK1) to maintain the normal function of mitochondria, and Park2 mutations and the dissociation are found in Parkinson’s disease." (PMID 25734985, 2015). "Parkin-mediated mitophagy, initiated by accumulation of PINK1 on damaged mitochondria, is thought to be mainly involved in Parkinson’s disease." (PMID 26268247, 2015). "Generally, in autosomal recessive forms of Parkinson’s disease, such as those involving PARK2, DJ-1 and PINK1, loss-of-function mutations are implicated, and these patients have an early onset of disease manifestation." (PMID 25820783, 2015). "Important genes related to mitophagy are PINK1 and PARKIN, both known to be mutated in familial forms of Parkinson's disease." (PMID 26550569, 2015).